RANBP10 (RAN binding protein 10)
Description:
May act as an adapter protein to couple membrane receptors to intracellular signaling pathways (Probable). Core component of the CTLH E3 ubiquitin-protein ligase complex that selectively accepts ubiquitin from UBE2H and mediates ubiquitination and subsequent proteasomal degradation of the transcription factor HBP1. Enhances dihydrotestosterone-induced transactivation activity of AR, as well as dexamethasone-induced transactivation activity of NR3C1, but does not affect estrogen-induced transactivation. Acts as a guanine nucleotide exchange factor (GEF) for RAN GTPase. May play an essential role in hemostasis and in maintaining microtubule dynamics with respect to both platelet shape and function (By similarity).
Synonyms: KIAA1464
Tractability: PROTAC: ubiquitination databases record sites on it; its protein half-life has been measured.
Gene: Protein-coding gene on chromosome 16 (67,723,070 to 67,806,560, reverse strand). Ensembl gene ENSG00000141084.
Subcellular location: Cytoplasm, cytosol; Nucleus
Pathways (Reactome):
Signal Transduction: MET activates RAS signaling
Gene Ontology:
Molecular function: protein binding; guanyl-nucleotide exchange factor activity; protein-macromolecule adaptor activity; beta-tubulin binding; small GTPase binding
Biological process: cytoskeleton organization; proteasome-mediated ubiquitin-dependent protein catabolic process
Cellular component: nucleus; ubiquitin ligase complex; cytosol; GID complex; cytoplasm; microtubule cytoskeleton
Genetic constraint (gnomAD): Loss-of-function variants: 24 observed, 70.01 expected, observed/expected ratio (o/e) 0.34, 90% interval 0.25 to 0.48. The upper end of that interval is the gene's LOEUF score, 0.48, which puts it in group 2 of 6, group 1 being the genes least tolerant of losing a copy. Missense variants: 678 observed, 823.75 expected, observed/expected ratio (o/e) 0.82, 90% interval 0.77 to 0.88. Synonymous variants: 310 observed, 323.78 expected, observed/expected ratio (o/e) 0.96, 90% interval 0.87 to 1.05.
Homologues: Orthologues: chimpanzee RANBP10 (99% identical), guinea pig RANBP10 (99% identical), pig RANBP10 (99% identical), rabbit RANBP10 (98% identical), macaque RANBP10 (98% identical), dog RANBP10 (98% identical), mouse Ranbp10 (98% identical), rat Ranbp10 (97% identical), zebrafish ranbp10 (79% identical), Drosophila melanogaster RanBPM (48% identical). Paralogues in human: RANBP9 (68% identical), SPRYD3 (17% identical), GID8 (10% identical).
Diseases named in the same sentence as RANBP10 in open-access papers:
RANBP10 is named in the same sentence as 12 diseases in open-access papers, as found by Europe PMC text mining. Sharing a sentence is not in itself a finding about the gene and the disease. The quoted sentences say what the papers report.
glioblastoma (3 papers, 2021 to 2025). The most malignant astrocytic tumor (WHO grade IV). "In contrast, the downregulation of RANBP9 in HEK293 cells increased cell proliferation, and the silencing of RANBP10 was found to reduce glioblastoma cell proliferation." (PMID 40883813, 2025). "However, since RANBP10 has been reported to promote glioblastoma cell growth and RANBP9 silencing can increase proliferation, we can speculate that these effects are likely cell type dependent." (PMID 40883813, 2025). "Apart from a potential tumor-promoting role in glioblastoma, the relevance of RANBP10 in cancer has not been addressed." (PMID 40883813, 2025). "RAN-binding protein 10 (RANBP10) promotes the stabilization of c-myc via binding to the region P4 of FBW7 promotor and inhibiting its transcription, which induces the progression of glioblastoma." (PMID 35814468, 2022). "The results demonstrated that the silencing of RANBP10 had no significant influence on the apoptosis in glioblastoma cells." (PMID 34671019, 2021). "However, the biological function of RANBP10 in glioblastoma (GBM) has not been studied." (PMID 34671019, 2021).
glioma (3 papers, 2021 to 2024). A benign or malignant brain and spinal cord tumor that arises from glial cells (astrocytes, oligodendrocytes, ependymal cells). "In our study, we performed the GESA analysis using the CGGA database and found that RANBP10 high expression was positively associated with c-Myc target genes in glioma." (PMID 34671019, 2021). "To determine the importance of RANBP10 in GBM progression, we performed the GESA analysis using the CGGA database and found that RANBP10 high expression was positively associated with cell cycle and metastasis in glioma." (PMID 34671019, 2021). "Interestingly, the GESA analysis using the CGGA database indicated that RANBP10 high expression was positively associated with c-Myc target genes in glioma." (PMID 34671019, 2021). "In addition, we analyzed the survival data from the CGGA database and found that RANBP10 high expression was implicated in the poor prognosis of glioma patients." (PMID 34671019, 2021). "Overexpression of RANBP10 was found in several cancer types, including brain and CNS cancer, gastric cancer, kidney cancer, and prostate cancer." (PMID 34671019, 2021). "To further investigate the role of RANBP10 in glioma, we analyzed the characteristics of glioma patients related to RANBP10 expression based on the CGGA database and the data demonstrated that RANBP10 expression was dramatically associated with grade and 1p19q_Codeletion_status in glioma." (PMID 34671019, 2021). "We analyzed the data from the CGGA database and revealed the negative correlation of RANBP10 and FBXW7 in glioma." (PMID 34671019, 2021).
liver cancer (1 paper, 2014). An epithelial or non-epithelial malignant neoplasm that arises from the liver. "RANBP10, IRF1 and ZNF395 were found to be down-regulated in liver cancer tissues, while the expression levels of NACC1 and MLST8 remained unchanged." (PMID 24599008, 2014).
malignant glioma (1 paper, 2021). A grade III or grade IV glioma arising from the central nervous system. "Indeed, CGGA and Oncomine database analysis showed that RANBP10 was clearly increased in malignant glioma." (PMID 34671019, 2021).
prostate carcinoma (1 paper, 2021). A carcinoma that arises from epithelial cells of the prostate gland. "In AR-positive prostate cancer cells, RANBP10 formed a protein complex with itself or RANBP9 and then elevated the transcription activity of AR." (PMID 34671019, 2021). "In AR-positive prostate cancer cells, RANBP10 was highly expressed and was responsible for the activation of AR, thereby contributed to prostate cancer development and progression." (PMID 34671019, 2021). "Previous studies showed that RANBP10 was overexpressed in prostate cancer cells and was responsible for androgen receptor (AR) activation." (PMID 34671019, 2021).
tumor (3 papers, 2021 to 2025). "In conclusion, our data indicated that RANBP10 promoted cell proliferation, migration, invasion, and tumor growth of GBM cells." (PMID 34671019, 2021). "Recent studies have demonstrated that RANBP10 played important roles in the cell cycle, spindle assembly, the reproductive system, and tumor progression." (PMID 34671019, 2021). "Taken together, these results indicated that RANBP10 promoted colony formation and tumor growth of GBM cells by targeting the FBXW7/c-Myc signaling pathway." (PMID 34671019, 2021). "Downregulation of RANBP10 significantly inhibited cell proliferation, migration, invasion, and tumor growth of GBM cells." (PMID 34671019, 2021). "To determine whether RANBP10 promoted GBM progression, we knocked down RANBP10 using the shRNA sequences and found that downregulation of RANBP10 significantly inhibited cell proliferation, migration, invasion, and tumor growth of GBM cells." (PMID 34671019, 2021). "In addition, orthotopic implantation assay was performed and demonstrated that RANBP10 downregulation dramatically retarded the tumor formation capabilities of U-87 MG cells." (PMID 34671019, 2021). "Due to the substantial number of ubiquitylation events that changes when their expression changes, RANBP9 and RANBP10 significantly impact NSCLC pathogenesis, including tumor cell proliferation and metabolism." (PMID 40883813, 2025). "In this study, we found that RANBP10 promoted GBM cell proliferation, migration, invasion, and tumor growth." (PMID 34671019, 2021). "Our results revealed that RANBP10 was overexpressed in GBM, and patients with high RANBP10 expression showed poor prognosis, suggesting that RANBP10 may act as a tumor promoter in GBM." (PMID 34671019, 2021).
cancer (1 paper, 2021). A tumor composed of atypical neoplastic, often pleomorphic cells that invade other tissues. "RANBP10 has been reported as a transcription regulator in human cancer." (PMID 34671019, 2021). "In addition, the Human Protein Atlas database analysis showed that RANBP10 was commonly expressed in malignant tumors." (PMID 34671019, 2021). "Furthermore, RANBP10 might function in the DNA Damage Response (DDR) of cancer cells due to the post-translational modification following genotoxic stress." (PMID 34671019, 2021).
infection (1 paper, 2014). The state of being infected such as from the introduction of a foreign agent such as serum, vaccine, antigenic substance or organism. "Although the function of RanBP10 in fungi is not well studied, up-regulation of this gene in Ps during the initial stages of infection of DF suggests that it may play a key role in mobilizing intracellular signalling pathways required for the fungus to invade host tissues." (PMID 25030912, 2014).
RANBP10 also shares sentences with these, for which no sentence is quoted: breast carcinoma (1 paper); gastric cancer (1); kidney cancer (1); non-small cell lung carcinoma (1).